CDK2 (cyclin dependent kinase 2)
Diseases named in the same sentence as CDK2 in open-access papers (continued):
Sharing a sentence is not in itself a finding about the gene and the disease.
breast cancer (continued). "This induction and expression of pS294 in wt ER-positive or ERmut-positive breast cancers can be prevented by CDK2 inhibitors, but not by CDK4/6 inhibitors." (PMID 29137354, 2017). "However, Roniciclib affected the protein and mRNA levels of both CDK2 and CDK4 in the MCF7 breast cancer cells after a treatment for 72 h (RT-PCR P = 0.008 and 0.022, respectively)." (PMID 28246384, 2017). "CDK2 expression was necessary for mammary tumors driven by LMW-E, suggesting that cyclin E may serve as a biomarker for the use of CDK2 inhibitors." (PMID 28107181, 2017). "While cyclin D1/CDK4 specifically mediates centrosome amplification triggered by H-RasG12D, H-RasG12D&c-Myc, and in HER2+ breast cancer cells, silencing of cyclin E or CDK2 have no impact on centrosome amplification in the HER2/Ras systems." (PMID 23886499, 2013). "We present data showing that knockdown of CDK4, but not of CDK2, imparts radiosensitivity to breast cancer cells and normal mammary epithelial cells by signaling an apoptotic program." (PMID 23886499, 2013). "Next, we targeted both Cdk2 and Cdk4 in non-tumorigenic and Her2+ breast cancer cells using independent siRNA duplexes." (PMID 23776583, 2013). "Phospho-CDK2 levels were enhanced in all three therapy-resistant model cells but not in the hormone-sensitive breast cancer cells such as MCF7 and ZR-75-1." (PMID 21834972, 2011). "In breast cancer cells, 1α,25 (OH) 2D3 has been found to inhibit tumor proliferation by binding to VDR, In ovarian cancer cells, 1,25 (OH) 2D3 upregulates p27 protein levels, inhibits cyclin E/CDK2 activity, leading to cell cycle arrest at G1 phase and suppression of proliferation." (PMID 41031356, 2025). "Currently, the safety and pharmacology of the CDK2/9 dual-target inhibitor Fadraciclib (NCT04983810), as well as selective CDK9 inhibitors KB-0742 (NCT04718675) and PRT2527 (NCT05159518), are being evaluated in patients with solid tumors, including breast cancer." (PMID 40949156, 2025). "SNS-032 is a CDK inhibitor targeting CDK2, 7 and 957,58 that exerts several anti-cancer effects, including reducing cell growth, inducing apoptosis, and inhibiting angiogenesis and invasion in various cancer types, including esophageal cancer, AML, breast cancer, and multiple myeloma." (PMID 38993666, 2024). "It has been hypothesized that visfatin promotes breast cancer survival through the ABL proto-oncogene 1 (c-Abl) activator of the transcription 3 (STAT3) pathway and via upregulation of the mRNA levels of cyclin D1 and cyclin-dependent kinase 2 (CDK2)." (PMID 36900364, 2023). "Furthermore, in breast cancer, SMYD3 drives cell cycle progression by upregulating the transcription of cyclin A1 whereas, in hepatocellular carcinoma, SMYD3 promotes proliferation through stimulating CDK2 transcription." (PMID 35406445, 2022). "Thus, it is suggested that the down-regulation of CDK2 in the combined treatment can arrest the TNBC cancer cell cycle and enhance the anti-proliferation effects, imposing a positive effect on the treatments for breast cancer." (PMID 35205737, 2022). "Given the mechanism that ACTL6A activated the MYC/ CDK2 axis, we hypothesized that a CDK2 inhibitor would have potentially therapeutic effects against TNBC in combination with the first-line chemotherapy drug of breast cancer, paclitaxel (PTX)." (PMID 33541412, 2021). "Several studies have demonstrated that inhibition of CDK2 could induce breast cancer cell apoptosis without damage to normal cells." (PMID 33466812, 2021). "Interestingly, we found that higher CDK2 and CDK4 expressions were associated with non-responsiveness of breast cancer patients to therapy." (PMID 34421361, 2021).
breast cancer (continued). "Furthermore, we demonstrated that the combined inhibition of CDK2 and CDK4/6 could be a promising approach for treating palbociclib-resistant breast cancer." (PMID 33260316, 2020). "In conclusion, based on results of our GSEA analysis and knowledge from clinical trials we suggest the highest potential of alisertib and mesupron for CDK2 and PLAU-targeted therapy of lymph node negative luminal A breast cancer patients with high risk of distant metastasis." (PMID 32947901, 2020). "Additionally, various anti-cancer agents exert medicinal effects by reducing the expression of CDK family proteins; e.g., flavopiridol induced cell cycle arrest through inhibition of CDKs in human breast cancer cells, and CYC202, a potent inhibitor of CDK2, reduced tumor growth in vitro and in vivo." (PMID 31731635, 2019). "We hypothesized that CDK2-mediated site-specific phosphorylation of EZH2 drives tumorigenesis and contributes to TNBC phenotype, and inhibition of CDK2/EZH2 axis by specific inhibitors may reverse the phenotypes, thereby rendering TNBC targetable by current breast cancer therapies." (PMID 31704972, 2019). "Therefore, we conclude that CCND1, which belongs to the components of CDK2 and the downstream molecules of HER-2 signaling in Breast Cancer signaling pathway, could promote G1 phase of NIH3T3 by participating in the synthesis and degradation of protein." (PMID 26511608, 2015). "Since CDK2 activity is a principal target for MYC stimulation of G1-S progression, we investigated whether differences in CDK2 activity might account for the differential effects of MYC depletion in breast cancer cells." (PMID 24444383, 2014). "Additionally, the ability of constitutive CCND1/CDK2 activity to replace MYC over-expression is consistent with gene amplification data in clinical breast cancer specimens that show CCND1 and MYC are not typically co-amplified." (PMID 23390492, 2013). "Even though CDK2 has been reported to mediate resistance to various adjuvant therapies against breast cancers, downregulation of CDK2 did not alter the sensitivity (IC50) to radiation in ER-PR-HER2- cells or in MCF10A cells relative to cells expressing control vector." (PMID 23886499, 2013). "Given the crucial role of cyclin/CDK2 complexes in promoting centriole overduplication, we sought to determine whether indirubin-derived small molecule CDK inhibitors can suppress centrosome amplification in breast cancer cells." (PMID 20565777, 2010). "This could be due to additional inhibition of CDK2 by alvocidib, as activation of the CDK2‐cyclin E pathway has been proposed as one of the resistance mechanisms to CDK4/6 inhibition and targeting CDK2 in addition to CDK4/6 overcame resistance to CDK4/6 inhibitors in breast cancer." (PMID 40415599, 2025). "Given our observation that CDK4/6-resistant breast cancer cells are markedly sensitive to the addition of INX-315 (IC50 <25 nmol/L), it is plausible that these combinations might be effective using low doses of selective CDK2 inhibitors, thereby improving the overall tolerability profile." (PMID 38047585, 2024). "Based on the reported PK inhibitory activity of isatin and benzofuran nuclei, specially, on the homologous CDK2 and GSK-3β kinases, a hybridisation strategy of these two privileged scaffolds was adapted to design dual CDK2/GSK-3β hybrid inhibitors which could target breast cancer." (PMID 33327806, 2021). "It was found in breast cancer cells that are resistant to palbociclib which the transcriptions of AP-1 and C-FOS were increased, and AP-1 blockade in combination with palbociclib could effectively inhibit cell proliferation and reduce pRb and CDK2 levels as compared to single agent treatment." (PMID 34123801, 2021). "However, there is little evidence of endocrine resistance between CDK2 and ER+ breast cancer." (PMID 33098638, 2020).
breast cancer (continued). "Furthermore, we hypothesize that the upregulated cyclin E activity in trastuzumab resistant HER2 positive breast cancer facilitates CDK2 mediated non-canonical Smad3 phosphorylation, resulting in cell cycle progression and oncogenesis." (PMID 29137393, 2017). "This, together with our demonstration of a negative correlation between gene expressions of E2F3, CDK2 and CCNA2 with IKBKB expression in breast cancer patients, implicates IKKβ in regulating cell cycle progression in cooperation with miR-125b." (PMID 38093346, 2023). "But also identified signalling pathways not previously known to mediate progesterone action in breast cancer cells, such as MNK1/EIF4E pathway and the connection between CDK2, Cdc25 and the MAPK pathway." (PMID 36034422, 2022). "Disappointedly, our ChIP assay showed that the ER did not interact with the CDK2 or CDK4 promoter regions, suggesting that BC-N102 downregulates the expression of CDK2 and CDK4 independent of the ER in breast cancer cell lines." (PMID 34421361, 2021). "Our ChIP assay showed that the ER did not interact with the CDK2 or CDK4 promoter region, suggesting that BC-N102 downregulated the expression of CDK2 and CDK4 independent of ER positivity in breast cancer cell lines." (PMID 34421361, 2021). "Cell cycle arrest induced by MYC knockdown was accompanied by a decrease in CDK2 activity, but inactivation of CDK2 did not selectively affect the viability of MYC-dependent breast cancer cells." (PMID 24444383, 2014). "Although CDK4 and CDK2 are promising targets in cancer therapeutics, their role in the response of ER-PR-HER2+ or ER-PR-HER2- breast cancer cells to ionizing radiation is controversial and not extensively explored." (PMID 23886499, 2013). "We further showed that the expression of E2F3, CDK2 and CCNA2 transcripts are negatively correlated with expression of miR-125b but not that of the homologous miR-125a in breast cancer patients, supporting an inhibitory relationship between miR-125b and these cell cycle regulators." (PMID 38093346, 2023). "In agreement with the results from the cell-cycle analysis, we found that the protein expression of the negative cell-cycle regulator P21 was markedly increased in breast cancer cells after ZLM-7 treatment, which was accompanied with decreased expressions of cyclin D1, CDK2 and CDK6." (PMID 35890172, 2022). "Specifically, Roniciclib selectively inhibits CDK2, not CDK4, in HR-NB but not in breast cancer, which results in new hypotheses regarding both CDK inhibition and cancer stem cell-like signatures." (PMID 28246384, 2017). "Similarly, targeting CDK1, but not CDK4/6 or CDK2, is selectively lethal to MYC-dependent human breast cancer cells." (PMID 25914884, 2015). "We found that targeting CDK1 rather than CDK4/6 or CDK2 selectively reduced the viability of MYC- dependent breast cancer cells, suggesting a potential therapeutic value of targeting CDK1 for MYC-driven human breast cancer." (PMID 24444383, 2014). "Therefore, our data do not support a synthetic lethal interaction between CDK2 inactivation and MYC activation in breast cancer cells." (PMID 24444383, 2014). "Although CDK2 inactivation has been reported to induce apoptosis in MYCN-amplified neuroblastoma cells, in this study, siRNA-mediated CDK2 depletion failed to induce apoptosis in breast cancer cells." (PMID 24444383, 2014).
melanoma (132 papers, 2008 to 2025). A malignant, usually aggressive tumor composed of atypical, neoplastic melanocytes. "The early stage of regeneration (1dpa) and melanoma is characterized by the upregulation of genes, including cdk2, mcm7, pcna, mki67, and cdk1, associated with proliferation and cell cycle." (PMID 38020918, 2023). "The analysis of the cell cycle profile of treated cells was examined by the evaluation of a marker of mitosis, Histone H3-pSer10, and a marker of the G1/S transition, Cdk2-pTyr15, to explore the mechanism underlying the inhibition of melanoma cell viability." (PMID 35877720, 2022). "Degrader 5 destroys CDK2/4/6 simultaneously and causes cell cycle arrest and apoptosis of melanoma cells, suggesting that PROTACs targeting CDK2/4/6 present a promising approach for treatment of cancers." (PMID 35327487, 2022). "Collectively this study suggested that the immune cell infiltrations of GBM and melanoma are inversely associated with CDK2/4/6 and STAT3 expression or genetic alterations." (PMID 33668805, 2021). "A clear link between melanocyte lineage transcription factor (MITF) and CDK2 expression levels has been observed in primary melanoma specimens and predict susceptibility to the CDK2 inhibition." (PMID 33805800, 2021). "NUAK2 is associated with melanoma tumor growth, both by controlling cell cycle progression via cyclin-dependent kinase 2 (CDK2), as well as by regulating migration." (PMID 34282782, 2021). "High expression of CDK2 causes melanoma patients to rapidly develop resistance to drug-targeted therapeutic agents, which leads to a decrease in OS." (PMID 33313406, 2020). "XL888 resistance mechanism involving CDK2 was identified in melanoma cells, and CDK2 expression was dependent on MITF (microphthalmia-associated transcription factor)." (PMID 31659567, 2020). "The conditional knockdown of CDK2 sensitizes the cells to Hsp90i and BRAFi treatments (Fig EV4F), clearly showing that CDK2 is a key player underlying melanoma resistance to both Hsp90i and BRAFi." (PMID 29507054, 2018). "It was found that the treatment of the melanoma cells with this compound caused a decrease of cyclin-dependent kinase 2 (Cdk2) as well as a decrease of the phosphorylated Rb (Retinoblastoma) protein." (PMID 28409496, 2017). "Suppression of miR-106b in A375 and Hs294t human melanoma cells caused inhibition of cyclin D1, D2 and E, and reduction in the expression levels of CDK2, CDK4 and CDK6 proteins in both cell lines." (PMID 25361006, 2014). "The G1 phase arrest in the melanoma cells after their treatment with anti-miR-106b was associated with marked suppression of the expression of both cyclins and CDKs (CDK2, CDK4 and CDK6) and concomitant reactivation of p21/WAF1/Cip1 protein." (PMID 25361006, 2014). "Expression of MITF has been associated with proliferation and survival of melanoma cells via its target genes CDK2, Bcl-2, livin, c-met, and HIF1α." (PMID 23349796, 2013). "Furthermore, among the differentially expressed genes associated with melanoma, the combination group significantly suppressed the transcript levels of key genes such as mitf, cdk2, and tyr, highlighting its potential therapeutic efficacy." (PMID 39598801, 2024). "G1 arrest in G361 melanoma cells exposed to eugenol has been associated with a decrease in the expression of cycle-related molecules including cyclins A, D3, and E, and cyclin-dependent kinases cdk2, cdk4, and cdc2." (PMID 37687080, 2023). "Both MITF and CDK2 could influence the expression of a number of genes associated with melanoma invasion, whilst being dynamically regulated by other genes within the melanoma cell." (PMID 36776379, 2022). "Analysis of the promoter DNA methylation indicated that among 30 TCGA cancer type hypo-methylation of CDK2 are significantly associated with T cell dysfunctional phenotype high death risk and shorter survival durations in melanoma, kidney, and brain cancer only." (PMID 33668805, 2021).
melanoma (continued). "With loss of NF1 and more recently an increase of CDK2 (in association with MITF) in melanomas being involved in the resistance to BRAF-inhibitor (BRAFi) therapy, we next sought to investigate whether miR-514a might be involved in this process." (PMID 25980496, 2015). "We also found that all of the NRAS mutated melanoma lines evaluated (or included in our panel) had low expression of CDK2, whereas there was some variability within the BRAF-V600E mutated group, with some cell lines harboring high expression of CDK2 and some with low expression." (PMID 23527225, 2013). "We have previously demonstrated that combined treatment with a CDK4/6 inhibitor and an MDM2 inhibitor suppresses the growth of melanoma patient-derived xenografts and that knockdown of CDK2 overcomes resistance to CDK4/6 inhibition." (PMID 40904502, 2025). "Through pathway enrichment analysis, four key melanoma-associated genes (PIM1, MEK1, CDK2, and PDK1) were identified as potential therapeutic targets." (PMID 40649898, 2025). "In 1014 melanoma cells, even with high-dose CDK2 inhibition, addition of the CDK4/6 inhibitor was required to suppress cyclin E1 levels." (PMID 40904502, 2025). "CDK2 induces resistance to BRAF and hsp90 inhibitors and a high ratio of CDK1 expression leads to resistance of melanoma patients to therapeutic agents which causes a significant decrease in OS." (PMID 39820173, 2025). "The high expression of MITF, β-catenin, and CDK2 indicates that honokiol is an efficient melanoma inhibitor." (PMID 40943669, 2025). "We also demonstrated that blocking CDK2 activity enhanced the response to CDK4/6 inhibitors in these melanoma models." (PMID 40904502, 2025). "Additional studies have demonstrated a role for CDK2 activity as a mechanism of resistance to CDK4/6is in melanoma." (PMID 40282469, 2025). "MITF target genes play important roles in melanoma survival, including inducing an increase in the expression of the antiapoptotic gene Bcl2, cell cycle-related gene CDK2, cell motility-related gene c-Met, and pigment production/secretion-related gene RAB27A." (PMID 39684511, 2024). "But another study using mouse B16–F1 melanoma cells showed that genistein prevented G1 to S phase transition via the suppression of cyclin E/CDK2 activity and induction of p21(Cip1/WAF1) expression." (PMID 38586368, 2024). "The irregular expression of CDK2 is often accompanied with the augmentation of its partner cyclins A and E in many human cancers as breast, endometrial, lung and thyroid carcinomas, melanoma, and osteosarcoma." (PMID 39479486, 2024). "Previous research has shown miR-10a-5p’s involvement in inhibiting chicken granulosa cell proliferation by targeting MAPRE1 to suppress CDK2, as well as suppressing melanoma cell proliferation and migration." (PMID 38275797, 2024). "In CM, the knockout of cyclin-dependent kinase 2 (CDK2) resulted in G0/G1 phase arrest, instigating early apoptosis of melanoma cells." (PMID 38589876, 2024). "In this study, quinazolin-4(3H)-one derivatives 47 were synthesized as CDK2 inhibitors, showing potent antiproliferative activity against melanoma (MDA-MB-435) and glioblastoma (SNB-75) cell lines." (PMID 38398626, 2024). "Oleacein induces cell cycle arrest in melanoma cells at the G1/S phase transition, followed by a significant increase in the phosphorylation of Cdk2, a crucial regulator of this transition, at Tyr15." (PMID 39203892, 2024). "In human melanoma cells downregulation of cyclin A and CDK2 while in murine cells cyclin E and CDK2 have been observed." (PMID 37687080, 2023). "NF-κB upregulated Myc and cycle regulator proteins, cyclin D1, and cyclin-dependent kinase 2, which further promoted melanoma growth." (PMID 37503344, 2023). "Downregulation of the E2F family of transcription factors except E2F6 was reported in studied malignant melanoma cell lines along with a time-dependent decrease in cyclin A, cyclin D3, cyclin E, cdk2, cdk4, and cdc2 expressions." (PMID 36362950, 2022).